SPP1 (secreted phosphoprotein 1)
Diseases named in the same sentence as SPP1 in open-access papers (continued):
Sharing a sentence is not in itself a finding about the gene and the disease.
tumor (continued). "In addition to staining pleomorphic tumour cells, SPP1 predictably showed strong staining in macrophages (including multinucleated giant cells) and other inflammatory cells (excluded from analysis), as well as malignant osteoid (basophilic/calcified osteoid)." (PMID 40790295, 2025). "This pattern suggests that SPP1 may function as a central mediator of immune remodeling in pyroptosis-high tumors, reinforcing tumor-promoting interactions between stromal and immune compartments." (PMID 41208987, 2025). "In addition, in terms of the overall signaling pathway intensity, SPP1 in the tumor group was more strongly expressed in NK/T cells, Neutrophils, and Myeloid cells." (PMID 41384115, 2025). "Further combination of VSIG4 with SPP1 blockade synergistically boosted anti-tumor activity." (PMID 39920772, 2025). "Moreover, SPP1 is frequently upregulated in malignant tumors, where it enhances tumor cell adhesion, migration, and immune evasion." (PMID 41391064, 2025). "This interaction between SPP1+ TAMs and fibroblasts appears to be a shared mechanism across multiple cancer types, where fibroblast‐macrophage communication fosters an environment conducive to tumour progression." (PMID 40395129, 2025). "We hypothesized that a combination strategy aiming to block the reprogramming of GAMs using a synthetic 7aaRGD peptide that targets SPP1/integrin signaling might overcome resistance to ICIs and reinvigorate anti-tumor immunity." (PMID 40281508, 2025). "Additionally, SPP1 signaling from malignant cells appeared to recruit APOE+ macrophages to tumor margins, and promotes macrophage polarization into APOE+ M2-like macrophages." (PMID 40303328, 2025). "Additionally, SPP1 influences immune cell infiltration and inflammatory responses, contributing to tumor aggressiveness and therapy resistance." (PMID 41391064, 2025). "Moreover, NF-κB activation can further elevate SPP1 levels, creating a feedback loop that aids tumor survival and growth." (PMID 41391064, 2025). "Our results suggest that tumor-derived SPP1 may similarly promote the polarization of macrophages into an immunosuppressive state, indicating that SPP1 could be a potential therapeutic target in ICB-resistant tumors." (PMID 40303328, 2025). "Hence, the TME in CRC is composed of specialized TAM subpopulations with opposing roles: immune coordination (C1QC+) with anti-tumor functions versus stromal activation (SPP1+) involved in tumor progression signaling." (PMID 41450739, 2025). "High levels of SPP1 expression are correlated with tumor aggressiveness and a poor prognosis." (PMID 40196737, 2025). "VSIG4 and SPP1 inhibition synergistically increased anti-tumor action." (PMID 40422244, 2025). "Comparative analysis of intercellular communication characteristics between tumor and normal tissues found: significantly enhanced communication intensity of factors such as SPP1 and MIF in tumor tissues; more active communication networks involving SPP1 and lectins in normal tissues." (PMID 40958861, 2025). "Spp1‐producing tumor‐associated macrophages (TAM) herald a negative outcome in many cancers due to their multipronged immunosuppressive role." (PMID 39639496, 2025). "In addition to hepatic differentiation markers, the expression of tumor-associated markers (GPC3, SPP1, SPINK1, and KPNA2) was examined across all cell models." (PMID 40862732, 2025). "Functional enrichment analysis indicates that SPP1+ macrophages could promote angiogenesis in tumor tissues." (PMID 40438108, 2025). "ST data further confirmed the spatial co-localization of tumor and immune cells, as well as the expression of co-inhibitory ligand–receptor pairs, such as SPP1/CD44 and MIF/CD74, highlighting the mechanism by which tumor cells promote immune escape through the expression of co-inhibitory factors." (PMID 40867511, 2025).
tumor (continued). "SPP1 expression is upregulated in ICCA tumor epithelial cells, and SPP1-CD44 interactions impede T cell proliferation, but immunosuppressive T cells in the TME may escape this suppression by reducing CD44 expression." (PMID 40070825, 2025). "Single-cell transcriptomics identified a tumor cell subpopulation (NB3) and two tumor-associated macrophage (TAM) subpopulations (SPP1+ TAMs and IGHM+ TAMs) closely associated with BBM and highlighted transketolase (TKT) as a key molecular marker for metastatic progression in NB." (PMID 40070366, 2025). "Furthermore, CXCL9+ TAMs were predominantly enriched in the tumor margin, while SPP1+ TAMs displayed consistently increased expression from normal to tumor core regions, suggesting their potential involvement in malignant progression." (PMID 40725473, 2025). "SPP1 is involved in the development of the conducive tumor microenvironment (TME) during initial tumor formation through angiogenesis and upregulation of various cellular processes including cell proliferation, adhesion, migration and inter-cellular communication." (PMID 39857756, 2025). "Given the critical role of SPP1 in promoting tumor invasiveness and poor prognosis, targeting SPP1 with inhibitors or antibodies might offer therapeutic benefits." (PMID 41391064, 2025). "Notably, cell-cell interaction analysis revealed that SPP1 signaling between TAMs and tumor cells and/or neutrophils dramatically decreased in TAMs from VSIG4-deficiency mice." (PMID 39920772, 2025). "Given the distinct functional roles of CXCL9+ and SPP1+ TAMs in shaping the tumor microenvironment, CS polarity could serve as a potential biomarker for stratifying patients in immunotherapy." (PMID 40230843, 2025). "As shown, pathways of PD‐L1, GP1BA, RESISTIN and SPP1 are exclusively activated in tumour." (PMID 39934971, 2025). "Furthermore, CXCL9 and SPP1 expression in macrophage polarization has been shown to orchestrate a spatially structured and tightly regulated network of tumor-promoting and tumor-inhibiting factors, involving diverse populations of tumor-associated cells." (PMID 40940867, 2025). "Most of these ligands are secreted by myeloid cells, represented primarily by SPP1+ macrophages, indicate that SPP1+ TAM may deplete other immune cells at the forefront of tumor invasion." (PMID 40191203, 2025). "SPP1 is predominantly expressed by certain macrophage subsets within the TME, many of which exhibit features of the senescence-associated secretory phenotype (SASP), further promoting tumor progression." (PMID 41391064, 2025). "Additionally, the interaction of SPP1 with CD44 plays a pivotal role in creating a pro-metastatic tumor microenvironment." (PMID 40559389, 2025). "Given that both CSC and Macro_SPP1 are implicated in the hypoxia-induced pathway, we hypothesize the presence of a localized network within the hypoxic region of the tumor that connects Macro_SPP1 and CSC, collaborating to exacerbate the HCC microenvironment." (PMID 38521868, 2024). "Importantly, while C1Q+ macrophage differentiation was independent of IL-1R signaling in EGCs, we found that IL-1-activated tumor EGCs drive monocyte differentiation into pro-tumorigenic SPP1+ macrophages via IL-6." (PMID 39030280, 2024). "However, the functional roles and mechanisms of tumor-derived SPP1 in shaping the pre-metastatic niche (PMN) and promoting lung-specific metastasis are unclear." (PMID 39529085, 2024). "SPP1 glycoprotein is involved in a variety of important physiological and pathological processes outside the cell, including cell migration, recruitment of inflammatory cells and tumor metastasis." (PMID 38329443, 2024). "Therefore, the exact biological roles of SPP1 + macrophages in tumor microenvironment (TME) warrants further exploration." (PMID 39696410, 2024). "Moreover, in a validation cohort of 68 HNSCC samples, we confirmed the prevalence of POSTN+ fibroblasts and SPP1+ macrophages in the tumor stroma." (PMID 38519500, 2024).
tumor (continued). "MMP7 and SPP1 levels were also higher in both CDKN2A+ tumor regions and nearby CDKN2A+ regions." (PMID 38888512, 2024). "In this study, we detected a subset of SPP1 + macrophages expressing SIRPα, characterized by high lysosome and phagosome activity, T cell suppression ability, and enhanced antigen presentation ability, which is similar to macrophages engulfed tumor cells." (PMID 39696410, 2024). "Moreover, tumor-derived SPP1 promoted neutrophil-dominant PMN formation by specifically targeting lung epithelial cells to secrete CXCL1 and subsequently boosted HCC lung metastasis through NETs formation." (PMID 39529085, 2024). "Tumor-derived osteopontin (OPN/SPP1) drives the resident fibroblasts to myCAFs." (PMID 39335478, 2024). "SPP1 has been correlated with poor prognosis when expressed by tumor cells." (PMID 39400127, 2024). "Previous studies had found that SPP1 involved in tumor progression by interacting with CD44." (PMID 38346944, 2024). "SPP1 + TAMs were characterized by increased expression of SPP1, macrophage receptor with collagenous structure (MARCO), and vascular endothelial growth factor A (VEGFA) and were associated with tumor angiogenesis." (PMID 38443595, 2024). "Tumor-derived SPP1 achieves this transition by engaging CD44 (bSE = 2.5) and ITGAV (bSE = 2.2)/ITGB3 (bSE = 2.7) on the fibroblast surface, which mediates signaling via AKT (AKT1 and AKT3) and ERK (ERK2 = MAPK1) to induce TWIST1 (bSE = 2.5)-dependent gene expression in BC." (PMID 39335478, 2024). "Compared to Mo detected in normal brains, Mo detected in PDOXs showed higher expression levels of genes associated with pro-tumorigenic TAMs (e.g., Cxcl13, Ctsd, Ccl4, Apoe) as well as Mg mimicry (e.g., Spp1, Trem2, Cst7, Tyrobp), further confirming an active crosstalk with tumor cells." (PMID 38566128, 2024). "Furthermore, the expression of SPP1 exhibited correlations with various factors, including tumor purity, macrophages, neutrophils, and DCs." (PMID 38329443, 2024). "Notably, SPP1 expression increased markedly with higher tumor grades, while KRT78 expression decreased progressively with advancing cancer stages." (PMID 39596132, 2024). "For example, the targeting of TREM2, SPP1 and MARCO is currently under extensive investigation, and the first in vivo studies demonstrated promising results associated with the inhibition of immunosuppression and further decreased tumor growth." (PMID 39516356, 2024). "Furthermore, CCK-8 assay results showed that SPP1 overexpression promoted tumor cell proliferation, but this effect disappeared after treatment with LY294002." (PMID 39557868, 2024). "We discovered that inhibiting SPP1 reversed the tumor progression and extended survival times caused by the overexpression of CEBPB in vivo, which was associated to change the number of SPP1/Integrin αvβ1/phosphorylated-Akt-positive M2 TAMs in the xenograft tumors." (PMID 38994023, 2024). "Highly expressed SPP1 enhances tumor cell proliferation through inhibiting autophagy and apoptosis." (PMID 38466483, 2024). "Furthermore, our above investigations have identified that proliferative tumor cells predominantly reside in close proximity to the triad structure, which comprises SPP1‐expressing macrophages, endothelial cells, and POSTN+FAP+ fibroblasts (middle)." (PMID 39716897, 2024). "However, the current knowledge regarding microenvironmental cues, promoting the differentiation of tumor-infiltrating monocytes towards SPP1+ TAMs or C1Q+ TAMs, remains limited." (PMID 39030280, 2024). "In summary, these findings suggest a crucial role for the SPP1 signalling pathway in the resistance mechanism, potentially influencing the chemotherapeutic resistance of tumour cells through cell–cell communication between SPP1+ macrophages and malignant cells." (PMID 38982317, 2024).
tumor (continued). "Furthermore, in immune-exclusion samples, the SPP1 signaling pathway demonstrated the highest activity in communication between tumor and immune clusters, and CCL19-CCR7 played a pivotal role in the self-communication of immune clusters." (PMID 39505867, 2024). "In our data, SPP1 + macrophages were primarily enriched in tumor tissues." (PMID 39696410, 2024). "Both TGFBI and SPP1 were observed to have high average normalized counts within tumor tissues." (PMID 38979413, 2024). "We found that the interaction of POSTN+ fibroblasts with SPP1+ macrophages, POSTN+ fibroblasts with tumor cells, and SPP1+ macrophages with tumor cells gradually increased from NT to Pre, E and A stages, which was also observed in separate analyses in P2, P10, and P13." (PMID 38519500, 2024). "Moreover, a pancancer study across 8 tumor types revealed that SPP1 + Macs presented the strongest M2 signature, whereas another study in CRC revealed that SPP1 + Macs also exhibited high M1 macrophage regulatory activity." (PMID 39726047, 2024). "Liver tumors grew less in Spp1−/− mice and the tumor-specific CD8+ T cells were less exhausted." (PMID 39372792, 2024). "However, the SPP1+ macrophage showed the highest M2 score (p < 2.2e−16), suggesting the anti-inflammatory and pro-tumor characteristics of M2-like macrophages." (PMID 38600248, 2024). "In contrast, SPP1+ or TREM2+ TAMs play an important role in the immune escape of the tumor cells." (PMID 38533207, 2024). "The SPP1 protein was mainly found at the cytoplasmic fraction of the tumor and normal tissues." (PMID 39727934, 2024). "Overexpression of SPP1 in tumor cells may promote activation of the PI3K/AKT signaling pathway, thereby enhancing tumor cell proliferation and invasion." (PMID 39323640, 2024). "Indeed, macrophage positivity for CXCL9 or SPP1 defined anti- and pro-tumor macrophage phenotypes better than classical M1/M2 hallmarks expression." (PMID 38542388, 2024). "Another study focused on HNSCC revealed that SPP1 + TAMs might enhance tumor intravasation and metastasis via the secretion of SPP1, CCL18, and CXCL8." (PMID 39726047, 2024). "Meanwhile, SPP1 + macrophages were also reported to contribute to tumor progression by prompting the invasiveness of tumor cells or T cell suppression, and the enrichment of SPP1 + macrophages was reported to predict unfavorable prognosis across multiple cancer types." (PMID 39696410, 2024). "Interestingly, there was a significant correlation between TGF-β, IL-6, TLR-2 and TLR-4 in the primary CRC tumor and SPP1 expression by macrophages in the metastatic intrahepatic tumor." (PMID 39372792, 2024). "Interestingly, the main tumor interaction networks include ECM components previously identified in the KEGG analysis (SPP1, FN1, collagens), cell–cell interactions and cholesterol along with apolipoprotein (adult)." (PMID 39482394, 2024). "Notably, ERRα was localized to the nucleus and SPP1 expression was generally cytoplasmic with a higher likelihood of co-expression in tumor samples than in the normal breast tissue." (PMID 39682141, 2024). "TAMs exhibited high levels of SPP1 relative to M0 macrophages and tumor cells." (PMID 38648200, 2024). "Our above results indicated that TAM exerted higher levels of SPP1 expression than tumor cells." (PMID 38648200, 2024). "Furthermore, we compared all significantly different signaling pathways between tumor and normal samples in detail, identifying pathways such as SPP1 and MHC-I as particularly active in tumors." (PMID 39850883, 2024). "This implies that KHDRBS1-positive HCC cells may modulate the HCC tumor microenvironment by affecting the functionality of SPP1." (PMID 38660302, 2024). "The expression of SPP1, Ki67 (tumor proliferation marker) and CD31 were detected by IHC staining." (PMID 38956502, 2024).
tumor (continued). "Remarkably, outgoing signals from CXCL10+ M1 Macrophages to B cells, CD4+T cell, CD8+T cells and Endothelial cell were more abundant and stronger in tumor group compared with normal group, while the output signal of SPP1+ macrophages cell was reduced in the tumor group." (PMID 39170612, 2024). "This analysis showed that the presence of UPP1high tumor cells was significantly positively associated with FOXP3+ regulatory T cells (Tregs), MMP11+ cancer-associated fibroblasts (CAFs), LAG3 + PDCD1 + CD8+ exhausted T cells, and M2-like SPP1+ macrophages." (PMID 38331898, 2024). "The role of SPP1-expressing TAMs in tumor progression is under intensive investigation." (PMID 39516356, 2024). "We found that TNF-α and IL-1β could increase the expression of OPN in both tumor cells and macrophages, which might be the reason for the increased number of SPP1 + Macs." (PMID 39726047, 2024). "Notably, HCC patients with high CSC levels exhibited an accumulation of SPP1+ macrophages (Macro_SPP1) expressing metalloproteinases (MMP9, MMP12, and MMP7) regulated by HIF1A, suggesting a hypoxic tumor region connecting Macro_SPP1 and CSC." (PMID 38521868, 2024). "Using these data, we observed that SPP1+ TAM is more enrich in tumor area in MLN than PT." (PMID 39236316, 2024). "However, utilizing FACS-sorting and EGC-specific genetic IL-6 and IL-1R depletion models, we confirmed the critical role of IL-1-triggered EGC-IL-6 release as a regulator of tumor growth and SPP1+ TAM differentiation." (PMID 39030280, 2024). "SPP1 + macrophages possessed a high phagocytic signature and could engulf more tumor cells in vitro and in vivo." (PMID 39696410, 2024). "MIHC staining revealed that SPP1 was substantially colocalized with CD68+ cells but barely colocalized with CD4+ T cells, CD8+ T cells or B cells and that SPP1 was more highly expressed in macrophages derived from HNSCC tumor tissues compared with those derived from adjacent normal tissues." (PMID 39726047, 2024). "We also suggest CAFs secreted CSF1 or FN1 could unidirectionally target cDC2, C1QC+TAMs, and SPP1+TAMs to promote macrophage or cDCs differentiation, as well as tumor development." (PMID 39323622, 2024). "In addition, several studies have indicated the presence of structural variations between tumor-derived SPP1 and other SPP1, which suggested a potential avenue for directly targeting tumor-derived SPP1 in the future." (PMID 39529085, 2024). "Consequently, targeting LGALS9 and SPP1 within the microenvironment represents promising targets for remodelling anti‐tumour immunity." (PMID 39422697, 2024). "Furthermore, the tumor immune microenvironment was affected by SPP1 as it increases the PD-L3 expression via the PI1K/AKT, JAK, and TGF-β signaling pathways." (PMID 38329443, 2024). "Interestingly, co-injection of tumor cells with IL-1R1−/− EGCs resulted in lower tumor growth and reduced infiltration of SPP1+ TAMs when compared with tumors co-injected with WT EGCs." (PMID 39030280, 2024). "Moreover, SPP1+ Macs accounted for 49.77% of the total myeloid cell population in tumor tissues but only 19.52% of the total myeloid cell population in adjacent normal tissues." (PMID 39726047, 2024). "Additionally, Macro_SPP1 also accumulated near the tumor boundary of cluster 3, constituting the immunosuppressive front for CSC maintenance." (PMID 38521868, 2024). "Notably, also in this model, deletion of IL-1R in EGCs impacted tumor growth and SPP1+ TAM expansion, suggesting IL-1R triggered EGC-TAM crosstalk as a broad mechanism across independent orthotopic CRC subtypes." (PMID 39030280, 2024).